AHR (aryl hydrocarbon receptor)
Diseases named in the same sentence as AHR in open-access papers (continued):
Sharing a sentence is not in itself a finding about the gene and the disease.
cancer (continued). "AHR antagonists inhibit immune suppression, and AHR agonists overcome chronic inflammation and autoimmune disorders in cancer patients." (PMID 39404411, 2024). "Multiple lines of evidence support a key role for AHR in cellular homeostasis, energy metabolism, immune cell responses, inflammation and cancer." (PMID 39450255, 2024). "This view has changed considerably with AHR now considered an important player in immunology as well as tissue and cancer biology." (PMID 39242971, 2024). "AhR can suppress the expression of MiR-96, which is closely related to the suppression of cancer development." (PMID 38518996, 2024). "The present study provides new insights into the diversity of AhR functions in the development of cancer including GC." (PMID 39200369, 2024). "Over the years, several studies have demonstrated activation of AhR plays a significant role in cancer initiation and promotion." (PMID 38448800, 2024). "This review article summarizes the state of knowledge of AhR activation on the TME, limitations of current findings, and the potential for modulation of the AhR as a cancer therapy." (PMID 38339226, 2024). "We have previously demonstrated that kynurenine released from adipocytes activates AhR leading to cancer progression in vitro." (PMID 39301545, 2024). "Several recent reviews have extensively described the role of AhR in the regulation of the immune system during cancer progression; thus, here we will briefly summarize some of the recent key findings." (PMID 38807762, 2024). "Although AhR expression was predominantly high in cancer cells, it was only found in 2.12% and 0.44% of T cells and macrophages, respectively." (PMID 38680496, 2024). "Direct investigations aimed at elucidating the precise role of AhR in specific disease settings are needed to fully understand its role in cancer." (PMID 38459088, 2024). "Given the important role of the AhR and its crosstalk in carcinogenesis targeting these signaling pathways offers the opportunity for improvement cancer prophylaxis and therapy." (PMID 39339278, 2024). "Recent work suggests that AhR activity antagonizes STING-mediated IFN-I expression in multiple cancer types including lung and muscle-invasive bladder cancer." (PMID 38459088, 2024). "However, the causal relationship between AhR and metabolic reprogramming in cancer remains unclear." (PMID 38434684, 2024). "‘Molecules with antagonistic AhR activity are being investigated as potential candidates for treatment of various cancers." (PMID 39211042, 2024). "This involves the activation of AhR signaling, concurrently enhancing cancer stem cell characteristics." (PMID 39351241, 2024). "Cluster 1 displayed the highest AhR expression in the cancer nucleus, whereas cluster 3 exhibited the lowest AhR expression in the cancer nucleus." (PMID 38680496, 2024). "Future studies are needed to explore if AHR‐mediated mitochondrial abnormalities precede the onset of muscle pathology such as that observed in models of cancer cachexia." (PMID 38333944, 2024). "Overexpressed in various tumors, AhR plays a key role in cancer development and the immune response, making it a promising therapeutic target." (PMID 38594256, 2024). "Kyn-activated AhR induces immunosuppressive effects and creates a microenvironment that is defective in organizing to eliminate cancer cells." (PMID 38518996, 2024). "Due to the importance of the immune system in carcinogenesis, the AhR pathway must play a significant role in cancer development." (PMID 38518996, 2024). "Aryl hydrocarbon receptor (AhR) is a fascinating molecule for cancer researchers who focus their work on barrier organs, since AhR is highly expressed in those tissues which are the primary sites of contact with ligands of AhR." (PMID 38518996, 2024). "AhR can be activated after inhalation of PAHs, which in turn triggers a series of events that promote the growth and spread of cancer." (PMID 38518996, 2024).
cancer (continued). "More studies identifying and testing the level of microbial metabolites activating AhR and their potential involvement in mediating cancer would shed new insights into managing cancer in a targeted therapy scenario." (PMID 38448800, 2024). "Activation of AhR is one of the reasons why Kyn is perceived as an oncometabolite, since AhR regulates growth promoting genes in cancer cells." (PMID 38188364, 2024). "Further studies are needed to evaluate in vivo biological tests for their use as new PET cancer AhR imaging agents." (PMID 39275108, 2024). "AHR activation has been shown to have both protumorigenic and anti‐tumorigenic effects, depending on the context and stage of cancer development." (PMID 38868519, 2024). "A correlation between NK infiltration and overall survival has been seen in multiple cancer types, and AhR activation appears to potentiate NK cell cytolytic activity." (PMID 38339226, 2024). "In this review, we attempted to highlight recent developments that point to a possible crosstalk between the AhR pathway and the microbiome in cancer initiation, promotion, and progression." (PMID 38448800, 2024). "In this section, we briefly discuss the function of specific stemness factors, such as OCT4, SOX2, and NANOG, which are involved in ROS homeostasis, such as the aryl hydrocarbon receptor (AhR)–Nrf2 axis in cancer development." (PMID 38791215, 2024). "Some studies suggest that activating the AhR by specific ligands promotes cancer, while others have shown that the AhR activation protects against the effects of environmental carcinogens." (PMID 38518996, 2024). "The next section of the review will discuss the crosstalk between AhR and microbiome in cancer development and progression." (PMID 38448800, 2024). "The mIHC results for NSCLC showed that AhR was predominantly expressed in the nucleus in cancer cells, in accordance with our findings." (PMID 38680496, 2024). "To thoroughly compare the five cancer types based on AhR expression, we applied a k-means clustering algorithm." (PMID 38680496, 2024). "These complex interactions indicate that the AHR’s function is context-dependent, making it a potential target for cancer-specific therapies, although more cancer-specific studies are needed for a comprehensive understanding." (PMID 39336758, 2024). "By investigating a large cohort of patients with different clinical parameters, we aimed to address the knowledge gap regarding the expression of AhR in various cancers." (PMID 38680496, 2024). "The IL6/STAT3 axis also increases TDO2, and consequent KYN production leads to the activation of AhR in response to inflammation in various types of cancer." (PMID 39311710, 2024). "The exact functions of AhR signaling during cancer development are still under investigation, and more studies are required to fully understand its role in the carcinogenesis." (PMID 38518996, 2024). "Reduced glucose uptake and mitochondrial activity are correlated with downregulated GLUTs due to 2,3,7,8-tetrachlorodibenzo-p-dioxin (TCDD)-activated AhR, which impacts glucose transport and utilization in pluripotent embryonal cancer cells." (PMID 38434684, 2024). "Formate is a bacterial fermentation product that is known to play a role in cancer, but its role in the crosstalk between gut microbiome and AhR is still unexplored." (PMID 38448800, 2024). "By attaching to various ligands, AhR regulates cancer metabolic reprogramming by dysregulating various metabolic pathways, including glycolysis, lipid metabolism, and nucleotide metabolism." (PMID 38434684, 2024). "Although targeting AhR in cancer has shown significant promise in pre-clinical studies, there has been limited efficacy in phase III clinical trials to date." (PMID 38339226, 2024). "Our findings reveal that AhR expression was primarily localized in cancer cells, followed by stromal T cells and macrophages." (PMID 38680496, 2024).
cancer (continued). "The modulation of the AHR has diverse effects on cancer cell behaviour in a cell-specific manner, influencing cell proliferation, invasion, and differentiation." (PMID 39336758, 2024). "Cancer initiation can be induced by disrupting the balance of cellular ROS maintained by the AhR–Nrf2 gene battery." (PMID 38791215, 2024). "AhR-null mice remain viable and fertile, making them ideal models to study cancer development and progression." (PMID 38807762, 2024). "DIM was found to reverse epithelial-mesenchymal transition (EMT) and prevent cancer cell metastasis by modulating AhR signaling and suppressing the NF-κB pathway." (PMID 39211042, 2024). "The Kyn-mediated Trp-Kyn-arylhydrocarbon receptor AhR pathway, which promotes immune cell differentiation and apoptosis, is also one of the immune escape mechanisms of cancer cells in inflammatory tumors or so-called hot tumors with lymphocyte infiltration." (PMID 39735553, 2024). "In the case of AHR therapeutics, the present application of AHR antagonists in cancer disorders is a reasonable strategy for preclinical trials." (PMID 39404411, 2024). "Dissecting the modulating activity of the AhR–Nrf2–ER axis by phytochemicals, in general, and the classes discussed in this review in preventing cancer initiation/promotion versus the induction of cell killing in advanced cancer cells is still a challenge." (PMID 39339278, 2024). "Ligand-activated AHR can inhibit or induce specific signalling pathways, impacting cancer cell functions." (PMID 39336758, 2024). "It has been established that activating AHR plays a critical role in cancer cell development, invasion, and metastasis [4‒6]." (PMID 38404179, 2024). "This information is essential before screening, developing, and applying AhR modulators for cancer chemoprevention." (PMID 38518996, 2024). "Some stilbene derivates were labeled with carbon-11 and fluorine-18 to develop six potential targets to monitor AhR expression as PET cancer imaging agents." (PMID 39275108, 2024). "In upper gastrointestinal tract tumors of the esophagus and stomach, a growing body of literature addresses the role for AhR in cancer progression." (PMID 38807762, 2024). "In this review, we aim to explore the role of AhR in the development of cancer that originates from barrier organs." (PMID 38518996, 2024). "The high degree of complexity emerging from AhR regulation and crosstalk with several signaling pathways contribute to its dual role in cancer." (PMID 39339278, 2024). "The dedicated interplay to control NRF2 and AHR master regulators of ROS homeostasis should be defined as the context-dependent nature of NRF2/AHR actions in each cancer case." (PMID 39404411, 2024). "Aryl hydrocarbon receptor (AhR) signaling promotes invasion and cancer stem cell properties in in vitro co-culture of Fn with CRC cells under this condition." (PMID 39100682, 2024). "AHR is recognized as an attractive therapeutic target because of its central role in coordinating cancer cell responses to metabolic changes, genetic alterations, environmental signals and immune activities." (PMID 39450255, 2024). "AHR is overexpressed in many cancer types and has been reported to exhibit diverse pro-survival functions." (PMID 39450255, 2024). "The aryl hydrocarbon receptor (AHR) is a ligand activated transcription factor which in certain cancer types drives pro-survival processes that facilitate tumorigenesis, malignant cell migration, invasion, and metastasis." (PMID 39450255, 2024). "Enzymes, such as indoleamine-2,3-dioxygenase 1 (IDO1), IDO2, or tryptophan-2,3-dioxygenase, catalyze this, thereby modulating immunity and fostering cancer progression via tryptophan depletion and aryl hydrocarbon receptor activation." (PMID 38732512, 2024). "Herein, we review the relationship between TME and metabolism and describe the important role of AhR in cancer regulation." (PMID 38434684, 2024).
cancer (continued). "AhR plays an important role in the developing several common types of cancer that originate from barrier organs, skin, lung, and gut." (PMID 38518996, 2024). "Previous studies have demonstrated that tryptophan derivatives, such as kynurenine and kynurenic acid, can activate AHR in various cancer models." (PMID 39690159, 2024). "Given the contrasting roles of AhR activation, and the potential consequences of systemic AhR blockade, additional factors need to be considered when developing strategies to target AhR in cancer therapy." (PMID 38339226, 2024). "Previous research has highlighted the dualistic nature of AhR signaling in cancer, where it can either suppress or promote tumorigenesis depending on the context." (PMID 39835132, 2024). "Kyn serves as a ligand for the transcription factor, Aryl Hydrocarbon receptor (AHR), which promotes growth pathways in cancer cells." (PMID 39763948, 2024). "To precisely assess AhR expression in cancer and immune cells, we conducted quantitative statistical comparisons." (PMID 38680496, 2024). "AHR is consistently active in a variety of human cancers and has several oncogenic functions, among them the mediation of pro-tumorigenic immunosuppression and epithelial-mesenchymal transition." (PMID 38361045, 2024). "Our findings further support targeting AHR with BAY2416964 as an innovative cancer treatment strategy." (PMID 39450255, 2024). "Since AhR is an emerging potential target for anticancer therapy, clarifying its role in specific cancer types is crucial to facilitate patient stratification." (PMID 38680496, 2024). "One strategy for modulation of AhR signaling in cancer treatment entails eliminating the pool of immunosuppressive AhR ligands, either through inhibition of tryptophan catabolism or by promoting clearance of the ligands." (PMID 38339226, 2024). "In addition to playing a role in cellular turnover, AhR signaling appears to influence the propensity of tumors to invade and migrate through modulation of cell adhesion, where the loss of cell adhesion molecules and signaling renders cancer cells more motile and invasive." (PMID 38339226, 2024). "In CRC cells, coculture of T18 cells with Fn was found to upregulate AhR, cancer stemness markers, CYP1A1, Wnt signaling, and MAPK signaling." (PMID 38448800, 2024). "In CLL, microarray analysis revealed high AHR mRNA and target genes expression relative to other human B-cell lineage cancers, suggesting an oncogenic role for AhR in the disease." (PMID 38807762, 2024). "DF 203 was originally identified as an anti-cancer agent and aryl hydrocarbon receptor (AhR) agonist." (PMID 38635505, 2024). "Recent data showed that different types of human cancers directly produce IL4I1 to form metabolites that activate aromatic receptors (aryl hydrocarbon receptor [AhR])." (PMID 38691253, 2024). "The activation of the AhR pathway by TCDD has been previously shown to enhance cancer cell invasion through metalloproteinases." (PMID 39200369, 2024). "Liver carcinogenesis induced by diethyl nitrosamine produced strong carcinomas in all AhR−/− mice but mostly premalignant adenomas in less than half of AhR+/+ mice." (PMID 38791215, 2024). "AhR inhibitor (BAY 2416964) is an open-label, Phase 1, first-in-human clinical trial for realistic evaluation of AhR inhibitors in cancer inhibition (NCT04069026)." (PMID 37830596, 2023). "This progress has created a multiple cell- and ligand-specific modulation of cancer progression which sparks an interest in AhR as a therapeutic target." (PMID 37241719, 2023). "It has been reported that the activation of AHR signaling is related with the motility ability of cancer cells, so we detect the effect of thymol on the migration of LUAD cells." (PMID 37655051, 2023). "Pioneering cutting-edge research works have provided fascinating new insights into the mechanistic role of AhR-driven downstream signaling in a wide variety of cancers." (PMID 37830596, 2023).
cancer (continued). "As immune regulatory enzymes, IDO1 and IDO2 have been found to be important targets of AhR to mediate immunosuppression and promote the growth of cancer cells." (PMID 37408267, 2023). "In fact, AhR appears to be involved in all of the major stages in cancer development, including cancer initiation, promotion, progression, invasion, and metastasis." (PMID 37696458, 2023). "Pharmacological targeting of AhR using different antagonists clearly gives convincing evidence about considerable role of AhR-mediated pathways in cancer progression." (PMID 37830596, 2023). "Collectively, these findings have underscored the significance of ‘personalized cancer medicine’, an evolving approach to cancer therapy that exploits the increasingly appreciated heterogeneous role of AhR-driven signaling among different subsets of patients." (PMID 37830596, 2023). "In fact, several in vitro and in vivo studies indicate pro- and anti-cancer effects of both AhR agonistic and antagonistic ligands in different tissues." (PMID 37241719, 2023). "IκB kinase α (IKKα) worked synchronously with AhR and transcriptionally upregulated cancer-stemness related gene network consisting of ABCG2, c-Myc, ALDH1A1, Lgr6 and KLF4." (PMID 37830596, 2023). "Either TDO or AHR was required for cells to express PD-L1 and for the expression of cancer stem cell properties." (PMID 37296860, 2023). "In the lung, AhR has been shown to induce the expression of ABCG2 and other critical genes involved in cancer stemness which has been found to be associated with an increase of stem population in osteosarcoma cells." (PMID 37696458, 2023). "This is via a mechanism involving AhR as an initiating event and the dysregulation of cancer-related genes as early key events, thereby confirming the Bhas 42 CTA as a suitable model for the study of the later steps in cancer progression." (PMID 36982734, 2023). "In multiple cancer models, AhR restricts stem cell proliferation by repressing pluripotency factors such as Oct-4, Sox2, c-Myc, and Nanog, and the expression or activation of AhR can promote differentiation in multiple cancer types." (PMID 37106727, 2023). "Specifically, the AHR drives cancer cell migration, invasion, and survival, regulates cell cycle progression and promotes cancer stem cell characteristics." (PMID 37696456, 2023). "These events collectively induce selective gene expression and regulatory mechanisms that determine the outcome of AhR activation to promote or suppress cancer in certain tissues." (PMID 37241719, 2023). "To investigate the expression of TET3 and AHR in cancer, we conducted an analysis using the TCGA database." (PMID 37718440, 2023). "Brominated alkaloid Isofistularin-3 (Iso-3), from the marine sponge Aplysina aerophoba induced de-methylation of AhR in cancer cells." (PMID 37830596, 2023). "AHR is involved in the occurrence of cancer as a ligand-activated signaling molecule through diverse signal pathways." (PMID 37274225, 2023). "Through AhR suppression, G0/G1 cell-cycle arrest, and apoptosis, anti-cancer action of quercetin was observed in a prostate cancer cell line." (PMID 36982245, 2023). "Collectively, these and other observations clearly indicate that the function of constitutive AhR varies and is cancer- and cell-specific." (PMID 37241719, 2023). "Since I3C is a ligand of the AhR, there is I3C-dependent activation of the mechanisms involved in the anti-cancer activity of I3C." (PMID 37633886, 2023). "has described, and largely proved, that interleukin 4 (IL‐4)‐induced gene 1 (IL4I1), a secreted enzyme belonging to the L‐amino‐acid oxidase family, was able to promote Aryl‐Hydrocarbon Receptor (AHR)‐driven cancer immunosuppressive ability." (PMID 38117000, 2023). "Formate fueled invasive abilities of cancer cells by activation of AhR-induced stemness of cancer cells." (PMID 37830596, 2023). "Recently, modulation of AhR signaling has attracted interest in the development of cancer immunotherapies." (PMID 37241719, 2023).